SLC7A11 (solute carrier family 7 member 11)
Diseases named in the same sentence as SLC7A11 in open-access papers (continued):
Sharing a sentence is not in itself a finding about the gene and the disease.
tumor (continued). "Subsequent multivariate Cox regression analysis revealed that sex, tumor location, and NRF2 nuclear expression and SLC7A11 expression were independent prognostic factors for OS." (PMID 34446045, 2021). "Taken together, SLC7A11 acted as a ceRNA for STX17, UVRAG, and RAB33B in 20, 12, and 12 different tumor types, respectively, and acted as a ceRNA for the three genes in 379 OC tissues and in 90 drug-resistant tissues." (PMID 34790572, 2021). "Clinically, we observed that the circFNDC3B and SLC7A11 expression was enhanced and miR-520d-5p expression was reduced in clinical OSCC tissues compared to the non-tumor tissues." (PMID 34434890, 2021). "Tumor cells with SLC7A11 knockdown exhibit higher vulnerability towards TMZ treatment and SLC7A11 inhibitors such as erastin and sorafenib potentiate a toxic impact of TMZ by induction of ferroptosis." (PMID 33401748, 2021). "SLC7A11 not only contributed to RCC prognostic assessment, but also resulted in metabolic reprogramming to fulfill the biosynthetic demands of tumor proliferation." (PMID 34761566, 2021). "After tumor immunotherapy, IFNγ released by activated CD8 + T cells downregulates the expression of SLC7A11 and SLC3A2, thereby inhibiting the uptake of cystine in tumor cells and enhancing LPO and ferroptosis." (PMID 34630843, 2021). "Cystine (CySS)/glutamate system xCT (SLC7A11) imports one of the building blocks of GSH, and tumor cells with high levels of GSH and high xCT expression are more resistant to APR‐246." (PMID 33314700, 2021). "Intriguingly, IFNγ released from CD8+ T cells downregulates the expression of SLC7A11 and SLC3A2, thereby limiting cystine uptake by tumor cells and promoting tumor cell lipid peroxidation and ferroptosis." (PMID 34312372, 2021). "Recent studies demonstrated that genetic deletion of SLC7A11 induces PDAC cell and tumor ferroptosis, and PDAC cells can use cysteine to synthesize GSH and coenzyme A to down-regulate ferroptosis." (PMID 33117704, 2020). "Zou’s group further dissected the mechanisms of IFN-γ-regulated tumor cell ferroptosis and found that IFN-γ regulates tumor ferroptosis by targeting SLC7A11 and SLC3A2." (PMID 32245497, 2020). "Three other amino acid transporters are highly expressed in tumor cells, including LAT1/SLC7A5, ATB0,+/SLC6A14, and xCT/SLC7A11." (PMID 33019627, 2020). "Second, we identified that expression of SLC7A11, a key component of system xC− that imports cystine for the formation of GSH, is a novel and robust predictive biomarker of tumour response to APR-246." (PMID 28348409, 2017). "Further, activation of the Nrf2-Keap1 signaling upregulates xCT (aka SLC7A11 or system Xc−) and amplifies glutamate secretion thereby impacting on the tumor microenvironment." (PMID 28805788, 2017). "We found that low-dose PTX down-regulated glutaminolysis-related genes (GLS, SLC7A11 and SLC1A5) and increased lactate production, resulting in decreased pH of the tumor microenvironment which inhibited tumor cell growth." (PMID 28522974, 2017). "Studies indicate that CD8+ T cells activated by immunotherapy can downregulate the expression of XCT subunits SLC7A11 and SLC3A2 on tumor cell membranes through the secretion of interferon‐gamma (IFN‐γ), enhancing intracellular lipid peroxidation and leading to tumor cell ferroptosis." (PMID 41560416, 2026). "Inhibition of central in vitro ferroptosis suppressors GPX4, GCLC, or SLC7A11 across these multiple models fails to impact established tumor growth." (PMID 41959261, 2026). "However, in lung squamous cell carcinoma, REV regulated the SLC7A11-HMMR interaction, activated ferroptosis, enhanced the cytotoxic effects on CD8+ T cells, and regulated the tumor immune microenvironment." (PMID 40552277, 2025).
tumor (continued). "or fermentation substrates (dietary fibers) aims to enrich SCFA-producing taxa that both (a) downregulate tumor antioxidant defenses (GPX4/SLC7A11) and (b) favor DC maturation and CD8+ T-cell priming—thereby lowering tumor ferroptosis thresholds while augmenting antitumor immunity." (PMID 41301464, 2025). "It is hypothesized that IKE and DIC might induce ferroptosis and modulate other biological processes by regulating SLC7A11 and NQO1 expression, potentially explaining the observed reduction in tumor volume in our experiment." (PMID 40007539, 2025). "However, USP5 facilitates the degradation of YBX3, leading to the stabilization of SLC7A11 and thereby promoting CRC cell survival and tumor progression." (PMID 41213937, 2025). "For example, hypoxic conditions in the tumor microenvironment induce lncRNA PMAN expression, which stabilizes SLC7A11 mRNA by promoting nucleoplasmic translocation of the RNA-binding protein ELAVL1 and ultimately inhibits iron death in peritoneal metastasis of gastric cancer." (PMID 40191204, 2025). "ORP100 treatment likewise suppressed chemotherapy‐induced GPX4 and SLC7A11 downregulation in vivo in BM cells but not in tumors when evaluated in an EG7‐implanted tumor model treated with 5‐FU or in a B16‐F10 tumor‐implantation model treated with cisplatin." (PMID 40932638, 2025). "Nonetheless, in the present study, we found that FXR could upregulate SLC7A11, indicating that FXR might be able to help tumor cells evade ferroptosis to some extent." (PMID 40681992, 2025). "In addition, tumor volume was significantly decreased in the HnRNPU-knockdown group, and this effect was reversed by SLC3A2 and SLC7A11 overexpression." (PMID 41310105, 2025). "This suggests that the anti-tumor effects of disulfidptosis may involve immunomodulatory mechanisms, potentially through CD8+ T cell functional inhibition or SLC3A2/SLC7A11-mediated cystine metabolism regulation impacting immune escape in ESCC." (PMID 40303412, 2025). "Biologically, SLC7A11 knockdown promotes ALOX12’s lipoxygenase activity to increase the peroxidation of PUFA-containing phospholipids, ultimately inducing ferroptosis and thereby inhibiting tumor progression." (PMID 40696490, 2025). "SLC7A11 gene expression is positively correlated with other amino acid transporters like SLC3A2, SLC1A5, GLS, and the infiltration of neutrophils and macrophages, suggesting that SLC7A11 plays a coordinated role in metabolic regulation and tumor immunity." (PMID 39973065, 2025). "Proteogenomics and transcriptomics have identified ferroptosis-related gene networks (e.g., GPX4, SLC7A11, ACSL4) as predictors of immunotherapy responsiveness, while single-cell RNA sequencing has revealed heterogeneity in ferroptosis sensitivity across tumor and immune subsets." (PMID 41562065, 2025). "Moreover, samples with upregulated SLC7A11 had higher TMB and TIDE values, and the expression level of SLC7A11 was positively related to the stromal score, the immune score, and the ESTIMATE score, while the gene was negatively related to tumor purity." (PMID 40978058, 2025). "However, DDR1 knockdown significantly reduced GSH levels and GPX4, SLC7A11 and ZEB1 expression and increased MDA and Fe2+ levels, as well as ACSL4, E‐cadherin, p‐YAP and p‐NF2 expression levels in tumour tissues." (PMID 40105492, 2025). "Consequently, GSH, SLC7A11, and GPX4 can be deemed as negative regulatory proteins for ferroptosis in tumor cells." (PMID 39822985, 2025). "Similarly, the cystine/glutamate transporter xCT (SLC7A11), highly expressed in GBM, imports cystine for GSH synthesis, bolstering tumor cells resistance to oxidative damage." (PMID 40775789, 2025). "While in the hypoxic tumor microenvironment, in contrast to the effects of HIF-2α, upregulation of HIF-1α in tumor cells enhances ferroptosis resistance by increasing cystine uptake, promoting SLC7A11 transcription, and lipid droplet formation." (PMID 40169575, 2025).
tumor (continued). "Moreover, SNHG12-mediated upregulation of SLC7A11 suppressed ferroptosis and promoted the adaptation of NSCLC cells to TAM2 polarization in the tumor microenvironment." (PMID 40417819, 2025). "High stromal expression of SLC7A11 is correlated with poor prognosis, unlike the high tumor expression of SLC7A11, which does not predict patient survival." (PMID 40427098, 2025). "Notably, the expression levels of SLC7A11 were significantly reduced in both MC38 cells after coculture with adipocytes for 48 h and in the tumor tissue of HFD-induced mice." (PMID 40141120, 2025). "Additionally, western blotting validates the expression of FTH1, GPX4, SLC7A11, FSP1 and DHODH in fresh surgical tumour tissues from three imatinib‐resistant patients compared with three imatinib‐sensitive patients receiving neoadjuvant imatinib therapy." (PMID 40866937, 2025). "Furthermore, efflux pumps (ABCB1, MRP1) and influx transporters (SLC7A11) significantly impact drug bioavailability, while age-dependent CYP metabolism and tumor-specific isoforms such as CYP2W1 represent metabolic vulnerabilities." (PMID 41425252, 2025). "Moreover, mregDCs are a specific DC subgroup that expresses high amounts of SLC7A11, and the KO of this gene combined with radiofrequency ablation (RFA) therapy resulted in increased tumor regression in a subcutaneous tumor model compared with RFA monotherapy." (PMID 40500404, 2025). "Further analysis from GEO (GSE#31210) showed that the expression of LAPTM4B and SLC7A11 was significantly increased in tumor samples compared to normal tissue." (PMID 38902268, 2024). "And knocking out SLC7A11 in these macrophages significantly diminished the infiltration of TAMs and hindered the shift to an M2-like phenotype in HCC tissues, which in turn attenuated tumor growth and metastasis." (PMID 38397869, 2024). "Additionally, plant metabolites and derivatives can regulate ferroptosis by targeting SLC7A11, GPX4, and ACSL4 and influence the immune status in the tumor microenvironment, providing new insights and directions for TCMs in cancer treatment." (PMID 38292937, 2024). "However, the staining intensity of the signature proteins—PML, G6PD, SLC7A11, and STMN1—in the tumor tissues was notably stronger than that in the paired adjacent tissues." (PMID 38317842, 2024). "Glucose uptake inhibitors can induce disulfidptosis of tumor cells with overexpression of SLC7A11, thus delaying cell proliferation without significant side effects." (PMID 38277541, 2024). "SLC7A11 interacts with tumor stem cell markers and has a negative impact on the prognosis in patients with HNSCC." (PMID 39350768, 2024). "Tumor samples show elevated transcript expression of both LAPTM4B and SLC7A11." (PMID 38902268, 2024). "ATM mediates the downregulation of SLC7A11 after radiotherapy, resulting in ferroptosis; this anti-neoplastic effect of radiotherapy is enhanced by the combination of immune checkpoint inhibitors, e.g., anti-PD-L1 or anti-CTLA4 antibodies, in tumor models." (PMID 38778030, 2024). "FLNB, SLC7A11, and CD2AP were lowly expressed in almost all major cell types, but significant expression difference was also found in fibroblasts between tumor and normal tissue." (PMID 38694875, 2024). "Based on these studies, we speculated that TRIM7 may activate ferroptosis by regulating the SLC7A11/GPX4 axis, thereby inhibiting tumor progression." (PMID 38509147, 2024). "Notably, SLC7A11 and SLC2A1 were identified as key genes for disulfide metabolism disorders in tumor cells and exhibited a high predictive value for OS." (PMID 38831301, 2024).
tumor (continued). "Notably, the knockout of the SLC7A11 gene or its inhibition effectively impeded cystine uptake and GSH synthesis, leading to significant inhibition of KARS mutant tumour cell growth." (PMID 38140764, 2024). "The SLC7A11/GSH/GPx4 axis serves as the central defense mechanism against ferroptosis, and downregulating the expression and activity of SLC7A11 has been shown to enhance the sensitivity of tumor cells to ferroptosis." (PMID 39040097, 2024). "The application of the DHODH inhibitor brequinar inhibited the growth of tumor cells with low GPX4 expression in vitro, and the combined treatment of brequinar and the SLC7A11 inhibitor sulfasalazine abolished the growth of tumor cells with high GPX4 expression." (PMID 38562175, 2024). "Additionally, the deletion of SLC7A11 selectively induced ferroptosis in pancreatic ductal adenocarcinoma cells driven by the KRAS proto-oncogene, effectively impeding tumor growth." (PMID 38475936, 2024). "Multivariate analysis showed that SLC7A11 mRNA was a predictive of poor survival independent of tumor grade, tumor size, and lymph node stage (p = .008) and the result remained significant within the luminal A tumors (p = .02)." (PMID 38073087, 2024). "In preclinical models, treatment with a glucose inhibitor can induce Disulfideptosis in cancer cells with high expression of SLC7A11, effectively suppressing tumor growth, and it has no significant toxicity to normal tissues." (PMID 38334964, 2024). "In contrast, tumour cells take advantage of stress-related transcription factors, including nuclear factor erythroid 2-related factor 2 (NRF2) and activating transcription factor 4 (ATF4), to increase SLC7A11 expression to combat ferroptosis." (PMID 38993573, 2024). "By investigating the correlation between SLC7A11 expression and immune cell infiltration in HNSCC, we aimed to uncover potential mechanisms through which SLC7A11 may influence the tumor microenvironment." (PMID 39350768, 2024). "Of note, Slc7a11-KD did not impede tumor cell growth in vitro, but significantly suppressed tumor growth in immunocompetent mice." (PMID 38360744, 2024). "The utilization of PD-L1 blockers elicits the secretion of IFN-γ by CD8+T cells, leading to the inhibition of transcription and expression of SLC7A11 and SLC3A2, thereby reducing GPX4 production via the JAK1/STAT1 pathway and facilitating ferroptosis in tumor cells." (PMID 38853203, 2024). "In summary, tumor cells may inhibit ferroptosis by increasing the expression of the deubiquitinating enzyme OTUB1, which prevents SLC7A11 degradation." (PMID 39769177, 2024). "In this mode of cell death, inhibitors of iron death, apoptosis, necrosis, and autophagy pathways failed to rescue glucose starvation-induced tumor cell death in SLC7A11 overexpressing cells." (PMID 38831301, 2024). "Interestingly, IFNγ produced by activated CD8+ T cells inhibits the expression of SLC3A2 and Solute Carrier Family 7 Member 11 (SLC7A11), components of the cystine/glutamate antiporter system xc-, promoting lipid peroxidation and ferroptosis in tumor cells." (PMID 39273090, 2024). "Moreover, SOCS2 and SLC7A11 were expressed oppositely in HCC clinical tissues and tumour xenografts with different radiosensitivities." (PMID 35995846, 2023). "In addition, we found that knockdown of SLC7A11 significantly enhanced the effects of VD on the size and number of tumour spheroids and the levels of Cys, GSH, ROS, and ferroptosis markers, such as SLC7A11 and COX2." (PMID 36846715, 2023). "IFNγ released by CD8 + T cells induces ferroptosis of tumour cells by activating the JAK-STAT1 pathway, inhibiting cysteine uptake, reducing LOOH to nontoxic LOH, and downregulating the expression of SLC3A2 and SLC7A11." (PMID 36600313, 2023).
tumor (continued). "However, SLC7A11’s role in cell death promotion in glucose-starved cells also indicates that its role in tumor biology is complex and likely context-dependent, although the exact context(s) in which SLC7A11 might have a tumor-suppressive function remains unknown." (PMID 37339981, 2023). "Notably, the high expression levels of SLC7A11 and GPX4 were related to tumour diameter, distant metastasis, and clinical stage of RCC (P<0.05) but not to age, sex, lymph node metastasis, or pathological differentiation (P>0.05)." (PMID 37807410, 2023). "The deletion of a system Xc_ subunit, SLC7A11, or a combination of GSH and coenzyme A blockade, or the administration of cyst(e)inases, could induce tumor-selective ferroptosis." (PMID 36942991, 2023). "Herein, we describe the tumor suppressive ability of miR-148a-3p in CRC SW480 and SW620 cells by inducing mitochondrial stress, lipid peroxidation, mitochondrial and intracellular iron accumulation, and ferroptotic cell death by SLC7A11 modulation." (PMID 37686618, 2023). "Collectively, our results demonstrated that CH‐OD‐SSZ hydrogel could inhibit SLC7A11/system xc− to induce the depletion of intracellular GSH and simultaneously inhibit GPX4 expression to promote the ferroptosis of tumor cells." (PMID 37132587, 2023). "They found that siRNA@ABMBP-COF could induce ferroptosis and apoptosis in HT1080 fibrosarcoma cells by downregulating SLC7A11 and HK2, suggesting the significant anti-tumor capacity in a tumor-bearing nude mouse model." (PMID 36819098, 2023). "This is because high SLC7A11 expression can increase the concentration of specific metabolites in tumour cells, such as GSH, which inhibits the activation of immune cells and the apoptosis of tumour cells, thereby reducing the efficacy of immune therapy." (PMID 37880315, 2023). "The result of the analysis revealed the expressional level of PDIA4, ATF4, and SLC7A11 in the RCC tumor is higher than the one in the adjacent normal tissue, respectively." (PMID 36906674, 2023). "In the GEO dataset, the expression of SLC7A11 was negatively correlated with the central memory CD8 T cells, effector memory CD8 T cells, immature dendritic cells, and type 1 T helper cells, all of which play an important role in killing tumour cells." (PMID 37880315, 2023). "In addition, the study also explored the mechanism and found that PDT can increase the sensitivity of tumor cells to ferroptosis by increasing the secretion of IFN-γ and down-regulating the expression of transporters (SLC7A11 and SLC3A2) on the cell membrane." (PMID 37894410, 2023). "The RT‐PCR results demonstrated that mRNA expression levels of SLC7A11, SLC1A5, and GCLM were notably up‐regulated and SAT1 was down‐regulated in HCC patients' tumor tissues compared with their ANLTs, which were consistent with the results from TCGA database analysis." (PMID 35841206, 2023). "Interestingly, recent evidence demonstrated that under ICB treatment, CD8+ T cells-derived IFN-γ downregulates the two key subunits (SLC7A11, SLC3A2) of the glutamate-cystine antiporter xCT, thereby promoting tumor ferroptosis." (PMID 36632216, 2023). "Our analysis indicates specific expression of SLC7A11 in MSCs, suggesting that MSCs or MSC-Exo may promote tumor cell disulfidptosis by enhancing SLC7A11 expression or function, potentially offering a novel direction for effective BC treatment." (PMID 38116315, 2023). "In summary, we describe a novel mechanism of ferroptosis in tumor cells based on the negative regulation exerted by YY2 on SLC7A11 transcription, and revealed a competitive, antagonistic regulation of YY1 and YY2 on the SLC7A11 promoter." (PMID 35246964, 2022). "In addition, we found that the expression level of SLC7A11 in the overexpressing HEPFAL group was lower than that of the control group, and the number of tumor cells in the overexpression HEPFAL group was the lowest." (PMID 36008384, 2022).